ALDOA (aldolase, fructose-bisphosphate A)
Diseases named in the same sentence as ALDOA in open-access papers (continued):
Sharing a sentence is not in itself a finding about the gene and the disease.
cervical cancer (5 papers, 2017 to 2025). A primary or metastatic malignant neoplasm involving the cervix. "ALDOA may increase the possibility of progression of cervical cancer." (PMID 36284631, 2022). "The process of aerobic glycolysis in cervical cancer cells is mediated by key enzymes such as glucose transporter 1 (GLUT1), LDHA, hexokinase 2 (HK2) and aldolase A (ALDOA), which enhance glucose uptake and lactate production, and promote the progression of cervical cancer." (PMID 36313645, 2022).
Obesity (5 papers, 2019 to 2025). Accumulation of substantial excess body fat. "DOC2A plus TLCD3B, was a top associated pair for BMI (obesity) and IQ (cognitive impairment), consistent with our data in zebrafish, CDIPT plus ALDOA the top pair for BMI, and KCTD13 plus MVP for IQ." (PMID 39988938, 2025). "It was reported that the etiology of obesity includes the up-regulation of AldoA." (PMID 37516743, 2023). "We then examined whether the serum ALDOA-Ab and FH-Ab levels correlate with clinical parameters such as sex, other diseases, lifestyle, and obesity." (PMID 34243715, 2021). "Moreover, the present study revealed the ALDOA-Ab levels were well associated with HT, CHD, and habitual smoking, but not with sex, DM, HL, alcohol abuse, and obesity." (PMID 34243715, 2021). "The ALDOA-Ab levels were well associated with blood pressure (P = 0.0022), CHD (P = 0.0400), and habitual smoking (P < 0.0001), but not with sex, DM, HL, alcohol intake, or obesity." (PMID 34243715, 2021).
prostate carcinoma (5 papers, 2022 to 2025). A carcinoma that arises from epithelial cells of the prostate gland. "Our work has highlighted GPI, PFKM, ALDOA, and PGK1 as key glycolysis-associated mRNAs that display CPSF1-dependent expression in prostate cancer cell lines." (PMID 39847481, 2025). "Supporting this, another study also showed that ALDOA interacts with DNA-PK to regulate glycolysis and that inhibition or depletion of DNA-PK led to a decrease in aldolase activity in castrate-resistant prostate cancer cells." (PMID 37704669, 2023). "Previous research studies have reported metabolic enzymes related to glycolysis, including PKM2, ALDOA, and ALDH3A1 carried by EVs that are closely related to the functionality of EVs to promote glycolytic metabolism of recipient cells and bone metastasis of prostate cancer cells." (PMID 40089067, 2025).
liver fibrosis (4 papers, 2024 to 2025). "IGF2BP2 increases the level of H3K18la by promoting the expression of the sugar metabolism-related gene ALDOA, thereby promoting liver fibrosis." (PMID 41199784, 2025).
Sepsis (4 papers, 2021 to 2023). Sepsis is defined as life-threatening organ dysfunction caused by a dysregulated host response to infection. "For example, in sepsis, ALDOA, and serpin B12, which were the proteins that showed higher increases, did not display significant changes in the turpentine model." (PMID 35743177, 2022). "In our case, ALDOA was detected in saliva, being a possible useful marker for sepsis condition." (PMID 36430174, 2022). "Therefore, ALDOA production is directly related to the presence of sepsis by acting as a promoter of bacterial adhesion to the host cell receptors to facilitate invasion, thus being a potent stimulator of immune response in humans." (PMID 35743177, 2022). "In our study, we constructed a machine learning model using five genes, including GTPBP2, ALDOA, PRKAR2A, KIF2C, and NHLRC2, to identify sepsis patients with a poor prognosis." (PMID 38054005, 2023). "In our investigation, we identified GTPBP2, ALDOA, PRKAR2A, NHLRC2, and KIF2C as genes related to sepsis death using three distinct techniques." (PMID 38054005, 2023). "Additionally, gender had no influence on the ALDOA activity in the validation study, but these results should be taken with caution and should be verified in a large population of pigs and also in pigs with sepsis produced by different infectious agents." (PMID 35743177, 2022).
ovarian carcinoma (3 papers, 2020 to 2025). A malignant neoplasm originating from the surface ovarian epithelium. "The silencing of lncRNA-NRCP could reduce the levels of glucose-6-phosphate isomerase ALDOA and ALDOC. lncRNA-NRCP via STAT1 could promote glycolysis in ovarian cancer cells." (PMID 33123468, 2020).
pancreatic ductal adenocarcinoma (3 papers, 2021 to 2023). An infiltrating adenocarcinoma that arises from the epithelial cells of the pancreas. "Next, we conducted IHC staining of pancreatic ductal adenocarcinoma (PDAC) tissues using antibodies against ALDOA, ATM and PLK1." (PMID 34565365, 2021).
viral infections (3 papers, 2014 to 2025). "In conditions of bona fide virus infection, the depletion of AldoA and EWSR1 inhibited, while the depletion of ILF3-90 stimulated the infectious virion yield of both viruses." (PMID 36306280, 2022). "Future studies will be required to define mechanistically how ALDOA acts to inhibit viral infections in insect cells." (PMID 24550726, 2014). "Third, investigating the mechanisms that trigger the anti-ALDOA immune response, such as viral infections or specific genetic backgrounds, could provide insights into the disease onset." (PMID 41200447, 2025).
autism (2 papers, 2016 to 2023). Persistent deficits in social interaction and communication and interaction as well as a markedly restricted repertoire of activity and interest as well as repetitive patterns of behavior. "For instance, we showed that ENO1 and ALDOA interact with MED13, which has been associated with a broad range of NDDs including encephalopathy, intellectual disability, and autism." (PMID 37664457, 2023). "GABPA was recently found to bind human-specific binding sites and regulate gene expression of at least four genes (ALDOA, HSPA8, TP73, and TMBIM6) that have been associated with cognitive diseases such as autism, AZ, PD and other brain disorders." (PMID 27014338, 2016).
Cirrhosis (2 papers, 2018 to 2021). A chronic disorder of the liver in which liver tissue becomes scarred and is partially replaced by regenerative nodules and fibrotic tissue resulting in loss of liver function. "High mRNA expression of HK2, PFKL, ALDOA, and PKM2 positively correlated with a progression of cirrhosis to HCC and a worse survival rate." (PMID 30430110, 2018).
Cognitive impairment (2 papers, 2020 to 2025). Abnormal cognition is characterized by deficits in thinking, reasoning, or remembering. "Endo-lysosomal proteins (e.g., HEXB, TPP1, SIAE) increased early in abundance alongside neurodegeneration-related proteins, and were followed by increases in metabolic proteins such as ALDOA, MDH1, and GOT1 at the mild cognitive impairment (MCI) stage." (PMID 40329321, 2025). "Namely, SMOC1, ALDOA, MAP1B and YWHAZ proteins emerged as biomarker candidates with low coefficients of variation that could best discriminate AD from non-AD cases with cognitive impairment as well as predict individuals with high Tau/Aβ ratio in CSF." (PMID 32514259, 2020). "SMOC1, YWHAZ, ALDOA and MAP1B emerged as biomarker candidates that could best discriminate between individuals with AD and non-AD cognitive impairment as well as Tau/β-amyloid ratio." (PMID 32514259, 2020).
colitis (2 papers, 2022 to 2024). Inflammation of the colon. "In vivo, PGK1 and ALDOA silencing enhances UCB salutary effects in trinitro-benzene-sulfonic-acid-induced colitis in NOD/scid/gamma humanized mice where control over disease activity and enhanced immunoregulatory phenotypes are achieved." (PMID 36131123, 2022). "Specifically, our results revealed decreased levels of glycolytic enzymes, including HK1, GPI, PFKL, ALDOA, and ALDOB in colitis." (PMID 38668322, 2024). "In Crohn’s disease, silencing of PGK1 and ALDOA restores Th17 cell ability to acquire an immunoregulatory phenotype in the presence of UCB and limits disease activity in a model of colitis in humanized mice." (PMID 36131123, 2022). "We observed a reduced relevant abundance for hexokinase (HK1), glucose-6-phosphateisomerase (GPI), phosphofructokinase (PFKL), fructose 1,6-biphosphate aldolase enzymes (ALDOA, ALDOB), triosephosphate isomerase (TPI), phosphoglycerate kinase 1 (PGK1), and alpha enolase (ENO1) in colitis." (PMID 38668322, 2024). "Silencing of PGK1 and ALDOA restores Th17 cell response to UCB in vitro, as reflected by an increase in the expression of immunoregulatory markers like the ectoenzyme CD39; and boosts UCB immunosuppressive properties in vivo, in an experimental model of colitis in humanized mice." (PMID 36131123, 2022).
COVID-19 (2 papers, 2021 to 2023). A disease caused by infection with severe acute respiratory syndrome coronavirus 2. "Consistent with increased glut-1 expression, upregulation of anaerobic glycolytic metabolism involving genes (LDHA, TPi, PGAM1, ALDOA) were identified in severe COVID-19 NKTs." (PMID 37029220, 2023). "Clustering and shared upregulation of glycolytic enzyme encoding genes GALM, GAPDH, GPI, and ALDOA together with HIF1A, and transcripts regulating exhaustion (TIGIT and LAG3) suggested that hypoxia/anaerobic axis is associated with impaired CD8+TM function in COVID-19 BALF." (PMID 37029220, 2023). "In CD14+ monocytes, HIF-1 signaling may regulate LDHA, ALDOA, TIMP1, ELOB and IFNGR2, and PPAR signaling may regulate UBC, RXRA, DBI and ACSL1 in COVID-19 patients." (PMID 33936072, 2021).
Crohn disease (2 papers, 2022 to 2025). A gastrointestinal disorder characterized by chronic inflammation involving all layers of the intestinal wall, noncaseating granulomas affecting the intestinal wall and regional lymph nodes, and transmural fibrosis. "At baseline, prior to UCB addition, PGK1 and ALDOA mRNA levels were higher in peripheral blood derived Th17 cells of Crohn’s disease patients, when compared to controls." (PMID 36131123, 2022). "Decrease in PGK1 and ALDOA mRNA levels was also noted in Th17 cells of Crohn’s disease patients although to a lesser extent than in healthy controls." (PMID 36131123, 2022). "PGK1 and/or ALDOA blockade might have therapeutic effects in Crohn’s disease by favoring acquisition of regulatory properties by Th17-cells along with control over their pathogenic potential." (PMID 36131123, 2022). "Th17-cells of Crohn’s disease patients display heightened PGK1 and ALDOA and defective response to unconjugated bilirubin." (PMID 40046063, 2025). "Unconjugated bilirubin modulates Th17-cell metabolism in Crohn’s disease by limiting glycolysis and through downregulation of phosphoglycerate-kinase-1 (PGK1) and aldolase-A (ALDOA)." (PMID 36131123, 2022). "Therefore, blockade of PGK1 or ALDOA should be considered as a potential immunotherapeutic strategy to boost AhR activation and ultimately control Th17 cell inflammatory potential while favoring the acquisition of suppressive features by these cells in Crohn’s disease." (PMID 36131123, 2022). "Th17-cells of Crohn’s disease patients display heightened PGK1 and ALDOA and defective response to UCB." (PMID 36131123, 2022). "Among the Kegg glycolysis DEGs, PGK1 and ALDOA were the genes most significantly impacted by exposure to UCB in both controls and Crohn’s disease patients." (PMID 36131123, 2022). "In Crohn’s disease, there was a positive correlation between the levels of PGK1 or ALDOA and Montreal type." (PMID 36131123, 2022). "Here we report that UCB controls glycolysis and downregulates glycolysis-related genes, mainly phosphoglycerate-kinase-1 (PGK1) and aldolase A (ALDOA), these effects being apparent in Th17 cells obtained from healthy individuals but not in those derived from Crohn’s disease patients." (PMID 36131123, 2022). "Importantly, exposure to UCB could reduce PGK1 and ALDOA levels in Th17 cells derived from the peripheral blood of healthy controls, after challenge with high concentration glucose; whereas such an effect was not present when considering Th17 cells derived from Crohn’s disease patients." (PMID 36131123, 2022).
glioblastoma (2 papers, 2019 to 2022). The most malignant astrocytic tumor (WHO grade IV). "In contrast, aldolase A (ALDOA) and aldolase B (ALDOB) revealed no significant prognostic impacts in the glioblastoma cohorts." (PMID 31450822, 2019). "Unlike ALDOA and ALDOB, we observed that ALDOC inversely correlated with histology stages through heat map analysis of TCGA glioblastoma cohort (p < 0.0001, n = 538)." (PMID 31450822, 2019).
glycogen storage disease (2 papers, 2018 to 2022). "CORO1A is associated with immunodeficiency 8, ALDOA is associated with glycogen storage disease 12 and ataxia‐telangiectasia‐like disorder 2, and EXOC6B is associated with intellectual disability and developmental delay." (PMID 30307717, 2018).
heart failure (2 papers, 2024). Inability of the heart to pump blood at an adequate rate to meet tissue metabolic requirements. "Contrastingly, in this cohort, expression of proteins associated with AMPK-encoding genes (PRKAA1, PRKAG1, PRKAA2, PRKAB1, PRKAB2 and PRKAG2) are significantly higher in oHCM patients, compared with other heart failure aetiologies, and expression of ALDOA is significantly down-regulated." (PMID 39200175, 2024). "ALDOA was significantly down-regulated in oHCM compared with non-heart-failure controls." (PMID 39200175, 2024).
intrahepatic cholangiocarcinoma (2 papers, 2021 to 2025). A carcinoma that arises from the intrahepatic bile duct epithelium in any site of the intrahepatic biliary tree. "For instance, high expression of ALDOA has been demonstrated to enhance aerobic glycolysis in intrahepatic cholangiocarcinoma and thereby promote proliferation and invasion of cholangiocarcinoma cells." (PMID 40518543, 2025). "In this study, we found that ALDOA was highly expressed in clinical intrahepatic cholangiocarcinoma (ICC) tissues, and its high expression was negatively correlated with overall survival (OS) and recurrence-free survival (RFS) in ICC patients." (PMID 33994862, 2021).
lymph node metastasis (2 papers, 2024 to 2025). "In multivariate analysis, lymph node metastasis, and ALDOA expression were independent risk factors." (PMID 38499636, 2024). "In contrast, in the subgroup analysis distinguishing GC patients with lymph node metastasis from those without, the IHC score indicated a markedly higher expression of ALDOA in the lymph node metastasis group compared to the non-lymph node metastasis group." (PMID 41049005, 2025). "The univariate analysis indicated neural invasion, depth of tumor invasion, lymph node metastasis, and ALDOA expression is a prognostic factor affecting the survival of CRC patients (P < 0.05)." (PMID 38499636, 2024).
muscular dystrophy (2 papers, 2019). Muscular dystrophy (MD) refers to a group of more than 30 genetic diseases characterized by progressive weakness and degeneration of the skeletal muscles that control movement. "Creatine kinase-muscle (CK-MM) and aldolase A (AldoA) levels are proven to be realistic biochemical markers to detect muscular dystrophy during osteoarthritic disorders (MD-OADs)." (PMID 31363397, 2019).
adenoma (1 paper, 2025). A neoplasm arising from the epithelium. "Additionally, the public data showed that ALDOA mRNA was upregulated in colorectal adenoma (P < 0.01), and was further elevated in colorectal adenocarcinoma (P < 0.001), suggesting the progressive elevation of ALDOA expression from adenoma to adenocarcinoma." (PMID 39755705, 2025).
anemia (1 paper, 2022). A reduction in the number of red blood cells, the amount of hemoglobin, and/or the volume of packed red blood cells. "In addition, the potentially related diseases to specific patients’ proteins were anemias or hematopoietic system diseases (proteins HBZ, EPB41, HP, PGK1, HBE1, BPGM, and ALDOA)." (PMID 36519745, 2022).
atherosclerosis (1 paper, 2021). A disease characterized by the build-up of fatty material and calcium deposition in the arterial wall resulting in partial or complete occlusion of the arterial lumen. "Subsequently, the ALDOA-Ab and FH-Ab levels for aCI (associated with atherosclerosis) were estimated using a conditional logistic regression model." (PMID 34243715, 2021). "Considering that max IMT is one of indices of atherosclerosis, both ALDOA-Abs and FH-Abs could reflect the degree of atherosclerosis." (PMID 34243715, 2021). "Atherosclerosis is a multifactorial disease, and the upstream atherosclerosis-inducing mechanism via hyperlipidemia could be different from that via hypertension, of which the latter pathway might be accompanied with the elevated expression of ALDOA and FH." (PMID 34243715, 2021).
atrial fibrillation (1 paper, 2025). A disorder characterized by an electrocardiographic finding of a supraventricular arrhythmia characterized by the replacement of consistent P waves by rapid oscillations or fibrillatory waves that vary in size, shape and timing and are accompanied by an irregular ventricular response. "A reduction of energy-producing proteins including glycolysis-related proteins, such as ALDOA and TPI1, and mitochondrial proteins, such as oxidative phosphorylation complexes, has also been reported in the arterial tissue of patients with atrial fibrillation." (PMID 41468454, 2025).
bile duct cancer (1 paper, 2025). "In liver and bile duct cancers, ALDOA's function is equally crucial." (PMID 40520908, 2025).
breast tumors (1 paper, 2017). "Given that ALDOA and hub genes could identify most cancers from normal controls using public datasets which were demonstrated above, we further examined the mRNA levels of ALDOA and several hub genes in breast tumors by RT-qPCR." (PMID 28191039, 2017). "RT-qPCR detection confirmed the relationship of ALDOA with CDC45 and CCNB2 in breast tumors." (PMID 28191039, 2017). "We further detect transcripts of ALDOA and several hub genes in breast tumors by RT-qPCR, and Pearson’s correlation analysis demonstrated a positive relationship of ALDOA with CCNB2 and CDC45, but not CDC20 and TK1, even a trend observed between them." (PMID 28191039, 2017).
calcific aortic valve disease (1 paper, 2025). "Consistently, in an ApoE−/− mouse model of CAVD induced by a high-fat diet, ALDOA K42la was also observed to promote aortic valve calcification, consequently increasing the risk of heart failure." (PMID 41440006, 2025).
coronary heart disease (1 paper, 2021). "In a correlation analysis, both ALDOA-Abs and FH-Abs were well associated with hypertension, coronary heart disease, and habitual smoking." (PMID 34243715, 2021).
diffuse large B-cell lymphoma (1 paper, 2022). "We have observed that the expression of ALDOA in DLBC (lymphoid neoplasm diffuse large B-cell lymphoma), GBM, LIHC and PRAD is positively correlated with the infiltration of CAFs and negatively correlated with BRCA-lumA, THCA and THYM (thymoma)." (PMID 35804089, 2022).
Emery-Dreifuss muscular dystrophy (1 paper, 2023). Emery-Dreifuss muscular dystrophy (EDMD) is characterized by muscular weakness and atrophy, with early joint contractures and cardiomyopathy. "CSRP3, LMCD1, ALDOA, PERM1: candidate genes for Emery-Dreifuss muscular dystrophy that may also provide insight into frailty-related muscle weakness?" (PMID 37936983, 2023).
endometriosis (1 paper, 2024). The growth of functional endometrial tissue in anatomic sites outside the uterine body. "In contrast to the normal endometrial and eutopic endometrium, our investigation demonstrated increased expression of ALDOA, PKM2, and LDHA in ectopic endometriosis." (PMID 38744310, 2024).